TYR (tyrosinase)
Diseases named in the same sentence as TYR in open-access papers (continued):
Sharing a sentence is not in itself a finding about the gene and the disease.
vitiligo (108 papers, 2005 to 2025). Generalized well circumscribed patches of leukoderma that are generally distributed over symmetric body locations and is due to autoimmune destruction of melanocytes. "Dysregulated TYR expression due to genetic variants can enhance oxidative stress in melanocytes, further contributing to their destruction and the progression of vitiligo." (PMID 40837363, 2025). "Polymorphisms in the TYR (tyrosinase) gene significantly impact the risk and development of vitiligo by affecting melanogenesis, oxidative stress, and immune response." (PMID 40837363, 2025). "Genetic studies further confirm shared susceptibility, identifying overlapping loci between vitiligo and autoimmune thyroid disease, including immune regulatory genes and organ-specific targets such as TYR, TG, and TSHR." (PMID 41303876, 2025). "Vitiligo is a progressive depigmenting skin disease characterized by depigmented white patches caused by the inhibition of the tyrosinase system, melanocyte loss, and activation of CD8 + T lymphocytes." (PMID 40707941, 2025). "Vitiligo was associated with a polymorphism in the gene that codes the main enzyme involved in melanin synthesis, tyrosinase (TYR gene)." (PMID 39421737, 2024). "Tyrosinase (TYR), a crucial enzyme in the production of melanindye, is commonly used as a diagnostic indicator for serious skin conditionssuch as vitiligo as well as melanoma cancer." (PMID 39473938, 2023). "Taken together, rs11614913 polymorphism of miR-196a-2 is associated with the development of vitiligo by affecting the expression of Tyrp1 and tyrosinase." (PMID 36187493, 2022). "This molecule inhibits tyrosinase in melanin synthesis, acting as another potential contributor to vitiligo pathogenesis; in fact, elevated levels are a known risk factor for cardiovascular disease." (PMID 37632859, 2022). "Both the tyrosinase and HLA-A2 encoding-genes are associated with vitiligo disease development, rendering relevance to tyrosinase-reactive T cells, as well as to the associated HLA-A*0201 restriction." (PMID 33335528, 2020). "Specifically, it has been reported that rhododenol caused vitiligo in Japan in 2014 and that rhododenol caused white spot damage on the skin by inhibiting enzymes involved in melanin production, such as tyrosinase, and inducing cell damage." (PMID 31561511, 2019). "Overall, these results indicate a clear relevance of CD8+T lymphocyte reactivity to melanocyte gp100 and tyrosinase in vitiligo, which suggesting a pathogenic role for gp100 and tyrosinase-specific T cells in vitiligo." (PMID 27821860, 2016). "Strength and relevance of this association (i.e., induction of T cell response against tyrosinase and gp100 and development of vitiligo) in our setting will be evaluated more in details in future studies with larger cohorts of patients." (PMID 25933939, 2015). "Recent research has focused on how polymorphisms in the TYR gene may contribute to the susceptibility and development of vitiligo." (PMID 40837363, 2025). "Furthermore, conventional tyrosinase inhibitors utilized in cosmetics, such as hydroquinone and its glycoside (arbutin), have also been linked to side effects such as erythema, vitiligo, skin allergies, dermatitis, acne, flaky skin, and dryness." (PMID 38921030, 2024). "Phenols act as tyrosinase analogs and interfere with melanin production, which may be associated with an increased risk of vitiligo caused by permanent hair dye use." (PMID 39624091, 2024). "Moreover, there exists significant epistasis between HLA‐A SNP rs12206499 and TYR SNP rs1393350,10 implying the interplay of the two polymorphisms in promoting vitiligo susceptibility." (PMID 33200838, 2021). "Diagnosis of TYR gene polymorphisms in vitiligo may inform personalised treatment strategies." (PMID 40837363, 2025). "In vitro studies have shown that vitamin D3 can enhance tyrosinase activity and stimulate melanogenesis, potentially contributing to repigmentation in vitiligo lesions." (PMID 41157208, 2025).
vitiligo (continued). "Genome-wide association studies (GWAS) have identified approximately 50 vitiligo-susceptibility genes, including PTPN1, PTPN22, NLRP1, FASLG, and TYR." (PMID 40837363, 2025). "In contrast, individuals suffering from vitiligo show a reduced activity of tyrosinase, leading to a decreased capacity of melanocytes to produce melanin, thereby forming white patches on their skin." (PMID 39852044, 2025). "Results from animal experiments demonstrated that the formulation exhibited excellent anti-vitiligo effects by increasing tyrosinase activity and regulating the body’s antioxidant mechanisms." (PMID 39852044, 2025). "The CT genotype of the PTPN22 rs2476601 polymorphism is more frequent in vitiligo patients; in the case of the NLRP1 rs2670660 polymorphism it was the AG genotype, and in the TYR rs1393350 polymorphism, it was the AG genotype." (PMID 40837363, 2025). "The inhibitory activity of vitamin C on tyrosinase (TYR), the rate-limiting enzyme for melanin synthesis, explains the skin-lightening properties of vitamin C and cast doubt on its use in vitiligo therapy." (PMID 41007740, 2025). "Excessive accumulation of kynurenine can also impair tyrosinase activity in vitiligo-affected areas, downregulate tyrosinase expression in melanocyte and keratinocyte co-cultures, and decrease melanosomes in 3D human skin models." (PMID 40703229, 2025). "Multiple studies have shown that vitamin D3 promotes repigmentation in vitiligo lesions by enhancing tyrosinase activity and stimulating melanogenesis, as observed in various in vitro experiments." (PMID 40772169, 2025). "Key elements in the development of vitiligo include oxidative stress and tyrosinase, which play significant roles in the disease’s pathological mechanisms." (PMID 39852044, 2025). "NB-UVB has been shown to promote the pigmentation of vitiligo lesions by inducing tyrosinase production and increasing the expression of HMB45 on the surface of melanosomes." (PMID 38159176, 2024). "A significant correlation has been established between melanocytes, tyrosinase (TYR), and the manifestation of vitiligo." (PMID 39596485, 2024). "We measured the level of tyrosinase in mouse skin, and the results showed a significant reduction in tyrosinase content in the skin of vitiligo mice." (PMID 38542385, 2024). "Tyrosinase underactivity results in vitiligo, or skin depigmentation, and hair lightening, whereas overactivity leads to an excess of melanin production and hyperpigmentation of the skin." (PMID 38645558, 2024). "A significant correlation has been observed between melanocytes, tyrosinase (TYR), and the manifestation of vitiligo." (PMID 39338414, 2024). "MBEHQ, depigmenting agent used in the treatment of extensive vitiligo, works by inhibiting the enzyme tyrosinase, which is involved in the production of melanin in the skin, leading to the lightening of the skin in areas affected by vitiligo." (PMID 39313936, 2024). "In the realm of mammals, tyrosinase not only contributes to the pigmentation of hair and skin, but it also influences skin conditions, giving rise to hypo (such as vitiligo) or hyper (manifesting as flecks or freckles) pigmentation." (PMID 38308284, 2024). "D206008 was found to increase the melanogenesis (melanin) concentration via the activation of the Akt/GSK-3ß/ß-catenin pathway, which links to an increase in MITF and TYR activity, as well as melanogenesis, suggesting a possible vitiligo therapy." (PMID 37371141, 2023). "miR-196a-2: Similar to miR-211, the rs11614913 miR-196a-2 polymorphism was found to influence the pathogenesis of vitiligo by affecting the expression of TYRP1 and tyrosinase." (PMID 37298095, 2023). "In vitiligo, melanocytes have a 3–5-fold excess of H4Bip, which inhibits tyrosinase, a key enzyme in melanin synthesis." (PMID 37686391, 2023). "Remarkably, all described antioxidants for melasma and vitiligo have evidence of a tyrosinase-inhibiting effect." (PMID 38136202, 2023).
vitiligo (continued). "The possible mechanism is that YQD can increase the expression and transcription of TRP-1 and enhance the activity of TYR, which is meaningful for the treatment of vitiligo." (PMID 38139842, 2023). "PMPP, a synthetic chalcone derivative that targets MITF and tyrosinase, has been proposed for vitiligo treatment, as PMPP dose-dependently increases both tyrosinase and MITF activities." (PMID 37371141, 2023). "Tyrosinase (a marker for melanogenic activity)-positive melanocytes were also significantly more frequently detected in most LS lesions than in vitiligo lesions (SA/EA: 0.007 ± 0.005 vs. 0.003 ± 0.004, p < 0.0001)." (PMID 37521337, 2023). "Only 6.5% of the LS samples showed less tyrosinase staining than the average of the vitiligo samples." (PMID 37521337, 2023). "MBEH can be metabolized by melanocytes, thus making melanocyte-specific proteins such as tyrosinase hemi-antigenic, which in turn leads to cytotoxic autoimmunity against pigment cells and induces vitiligo." (PMID 37108153, 2023). "Transgenic animal models include TCR transgenic mouse models of PMEL, TRP, or TYR, and these mouse models of vitiligo induced by immunity are mainly used for studies related to immune mechanisms." (PMID 37108153, 2023). "Serum homocysteine levels are elevated in patients with vitiligo, and homocysteine can increase oxidative stress and inhibit the melanin synthesis enzyme, tyrosinase." (PMID 37737154, 2023). "Electron transfer from an enzyme to a pterin triplet can inactivate the enzyme, in particular tyrosinase, which becomes a significant problem in vitiligo disease." (PMID 37686391, 2023). "Previous studies have reported that melatonin and its metabolites inhibit tyrosinase activity in human skin melanocytes, and the local melatonin supplements protect skin from oxidative damage during vitiligo." (PMID 37032347, 2023). "Tetrahydrobiopterin regulates the tyrosinase activity in melanosome, and the synthesized tetrahydrobiopterin is highly activated in vitiligo." (PMID 36969181, 2023). "Genome-wide association studies (GWAS) have identified more than 50 genetic risk variants for vitiligo, including genes related to cytolysis (GZMB, CTLA4, FOXP3) and melanocyte function (TYR, MC1R, XBP1)." (PMID 36182982, 2022). "Melanocyte-specific antigens recognized by CD8+ T-cells, such as MelanA, tyrosinase, gp100, and tyrosinase-related proteins 1 and 2, are detected in greater numbers in the peripheral blood of patients with vitiligo when compared to controls." (PMID 35643735, 2022). "Ultimately, TYR, TYRP1, DCT, and LARP7 have been screened as candidate biomarkers associated with vitiligo." (PMID 34107850, 2021). "AhR−/− mice showed lower tyrosinase activity, and mutations of the AHR gene were also associated with vitiligo susceptibility." (PMID 33381211, 2020). "TYR and TRP-1 are critical for the synthesis of melanin, the loss of which contributes to the development of vitiligo." (PMID 32267311, 2020). "The mechanism of KBL against vitiligo is related to the up-regulated expression of tyrosinase in melanin cells, enhanced activity and induced synthesis of melanin." (PMID 31781265, 2019). "Psoralea corylifolia L., (P. corylifolia), which is used for treating vitiligo in clinic, shows inhibitory and activating effects on tyrosinase, a rate-limiting enzyme of melanogenesis." (PMID 30400170, 2018). "NB-UVB increased the expression of MITF and tyrosinase during melanocytic differentiation and is currently used in clinical vitiligo phototherapy." (PMID 29019940, 2017). "CD8+T cell reactivity to gp100 and tyrosinase-originated peptide epitopes (P28 and P119) were significantly higher in vitiligo patients and was marked with CD8+T cell proliferation rate significantly increased compared with irrelevant peptides." (PMID 27821860, 2016).
vitiligo (continued). "Recent studies suggested the key role of CD8+T lymphocytes for mediating immune response in vitiligo through melanocyte differentiation antigens, including tyrosinase, gp100 and MelanA/Mart-1." (PMID 27821860, 2016). "In this study we demonstrated an increasing frequency of gp100 and tyrosinase antigen-specific CD8+T cells in the circulation of HLA-A*0201-positive vitiligo patients." (PMID 27821860, 2016). "The study aimed to evaluate the oxidative stress level and tyrosinase activity in vitiligo patients and to compare them with healthy volunteers." (PMID 20418970, 2010). "The melanocyte percentages and tyrosinase mRNA presence in normal skin and vitiligo areas, before and after curettage and grafting, were compared." (PMID 16389417, 2005). "Five out of sixteen (31.25%) tyrosinase mRNA-negative vitiligo lesions showed silver stain for melanin in basal cell layer kerati- nocytes before grafting." (PMID 16389417, 2005). "The homogeneous pigmentation, recovery to normal melanocyte percentage in the epidermal basal layer, and shift to positive tyrosinase mRNA state, are all favorable points regarding the efficacy of the proposed graft technique for longstanding vitiligo lesions." (PMID 16389417, 2005). "Notably, major alleles of TYR-related signal nucleotide polymorphisms (SNPs) are associated with vitiligo, while minor alleles are linked to MM, suggesting an inverse genetic relationship, as antityrosinase expression might protect patients with vitiligo against MM." (PMID 40807166, 2025). "IDO1, the rate-limiting enzyme in the kynurenine pathway, the excessive activation of the KYN pathway can diminish tyrosinase activity in vitiligo-affected areas, inhibit tyrosinase expression in MCs and KCs co-cultures, and reduce melanosome numbers in the 3D human skin reconstruct model." (PMID 40703229, 2025). "Therefore, the clinical treatment of vitiligo focuses on reducing oxidative damage and enhancing tyrosinase activity." (PMID 39852044, 2025). "Therefore, it is of interest to report the molecular docking analysis of tyrosinase (PDB: 1WX3) withcompounds from poly-herbal formulation for vitiligo treatment." (PMID 40599915, 2025). "Thus, the phytochemicals in the poly-herbal formulation enhancethe activity of the tyrosinase enzyme, supporting melanogenesis, making it a potential treatment for vitiligo." (PMID 40599915, 2025). "The present study concluded that LDM alone or LDM (+NB-UVB) can induce melanin synthesis by increasing the tyrosinase activity in melanocytes by limiting the oxidative stress, and this may be therapeutically exploited as an adjuvant therapy for vitiligo." (PMID 39594565, 2024). "In particular, estrogens act through the stimulation of tyrosinase activity in melanocytes, so that the use of estrogens and progesterone in the prevention of vitiligo was hypothesized." (PMID 39735711, 2024). "From a molecular perspective and tyrosinase (TYR) tend to be reduced in expression in vitiligo models and clinical, and the expression of cholinesterase (CHE) may increase." (PMID 37575231, 2023). "Interestingly, tyrosinase staining showed the most significant difference in melanocytes between LS and vitiligo." (PMID 37521337, 2023). "Furthermore, in the FHB therapy group, the levels of CHE in the peripheral blood of vitiligo mice were much lower, but the levels of TYR were significantly greater than in the model group." (PMID 37575231, 2023). "Targeting STAT3 with miR-21-5p can decrease apoptosis in melanocytes and increase tyrosinase activity, which could be a potential treatment for vitiligo." (PMID 37731844, 2023). "In conclusion, L. shawii methanolic extract stimulates melanocyte functions, including melanin production, and its derivative Metabolite 5 enhances tyrosinase activity, suggesting further investigation of the L. shawii extract-derived Metabolite 5 as a potential natural drug for vitiligo treatment." (PMID 37197407, 2023).
vitiligo (continued). "After entering melanocytes, MBEH is metabolized by tyrosinase to form superoxide ions, which then form hydrogen peroxide to promote the destruction of lipid and protein structures to form specific antigens, and further induce vitiligo." (PMID 37108153, 2023). "Skin inflammation in vitiligo also affects the synthesis of TYR." (PMID 37575231, 2023). "It was found that H2O2 could induce the expansion of endoplasmic reticulum and hinder the output of functional tyrosinase from the endoplasmic reticulum of melanocytes, thus resulting in the pathogenesis of vitiligo." (PMID 35777015, 2022). "Another significant non-HLA association with vitiligo found in Europeans was observed for the TYR gene, which regulates melanin biosynthesis in melanocytes." (PMID 35643735, 2022). "We propose the hypothesis that in the future natural drugs with anti-oxidant and anti-autoimmune properties are used in vitiligo progression phase and natural drugs with improved tyrosinase activity are used in stability phase." (PMID 34858164, 2021). "Previous studies have reported that melanocyte signal pathway is one of the core signal pathways in vitiligo, dominating melanocyte production, destruction, and pigment transport as transcription factors of melanocyte signal pathway, TYR, TYRP1, and DCT involved in vitiligo progression." (PMID 34107850, 2021). "TYR, TYRP1, DCT, and LARP7 were selected as biomarkers associated with vitiligo." (PMID 34107850, 2021). "Studies suggest that vitamin D3 increases tyrosinase activity and melanogenesis in vitro, which may lead to repigmentation in vitiligo skin lesions." (PMID 35111426, 2021). "In summary, we found that TYR, TYRP1, DCT, and LARP7 are biomarkers associated with vitiligo." (PMID 34107850, 2021). "The weak percentage of tyrosinase inhibition obtained with 13a shows that the combination of para and ortho hydroxyl groups is required to get potent tyrosinase inhibitors and subsequently, promising therapeutic agents to treat skin diseases (hyperpigmentation, lentigo, vitiligo and skin cancers)." (PMID 32019195, 2020). "Moreover, KBL was found to modulate vitiligo via the regulation of activity of multiple series enzymes such as tyrosinase (TYR), oxidoreductase (GSTP1, CAT, MPO, and GSTM1), and controlling signal transducer (NFE2L2)." (PMID 31781265, 2019). "However, due to severe adverse effects such as redness, skin peeling, and vitiligo, the application of commonly used whitening agents with strong TYR inhibitor activities, such as arbutin, kojic acid, and hydroquinone, are limited." (PMID 30224716, 2018). "Several melanocyte autoantigens have been detected in vitiligo patients including tyrosinase, tyrosinase-related protein 1, tyrosinase-related protein 2, melanosomal matrix protein gp 100 (Pmel17), melanocyte transcription factor (SOX10), and melanin concentrating hormone receptor 1 (MCHR1)." (PMID 29362715, 2017). "An increased level of homocysteine, which is a tyrosinase inhibitor, may also be a contributing factor to the development of MetS in vitiligo patients." (PMID 28443562, 2017). "Our studies identified two novel epitopes originated from proteins of gp100 and tyrosinase, which may have implications for the development of immunotherapies for vitiligo." (PMID 27821860, 2016). "Our studies identified two novel epitopes originated from proteins of gp100 and tyrosinase, which may contribute to the immunotherapy of vitiligo." (PMID 27821860, 2016). "However, whitening products with potent tyrosinase inhibitor activity such as kojic acid, arbutin, and hydroquinone have severe side effects, including vitiligo, and skin peeling and redness, thus limiting their application." (PMID 27827938, 2016). "At the same time, in patients with thyroid autoimmunity increased ROS levels have been demonstrated which might contribute to modify tyrosinase or other melanogenic proteins into neoantigens, leading to the appearance of vitiligo." (PMID 25838868, 2015).